METTL3 (methyltransferase 3, N6-adenosine-methyltransferase complex catalytic subunit)
Diseases named in the same sentence as METTL3 in open-access papers (continued):
Sharing a sentence is not in itself a finding about the gene and the disease.
cardiac hypertrophy (38 papers, 2020 to 2026). "A comprehensive analysis of METTL3-mediated m6A modifications in cardiac hypertrophy revealed that mRNAs encoding protein kinases, such as the mitogen-activated protein kinase family, exhibit m6A-specific enrichment." (PMID 40290189, 2025). "In the present research, we found that increased METTL3, coinciding with miR-221/222, mediated the cardiac hypertrophy caused by Ang-II." (PMID 35836108, 2022). "It was reported that miR-221/222 was associated with cardiac hypertrophy and promoted by METTL3 in an m6A-dependent manner." (PMID 35836108, 2022). "According to a previous report, a cardiac-hypertrophy-associated piRNA is demonstrated to inhibit the m6A modification of the target gene of METTL3 by competitively binding to METTL3." (PMID 34645714, 2021). "A cardiac-hypertrophy-associated piRNA is demonstrated to inhibit the m6A modification of the target gene of METTL3 by competitively binding to METTL3." (PMID 34645714, 2021). "Cardiac hypertrophy-associated PIWI-interacting RNA (CHAPIR) competitively binds METTL3 and blocks m6A methylation of polymerase family member 10 (PARP10), while up-regulation of PARP10 facilitates glycogen synthesis and pathological cardiac hypertrophy by inhibiting the kinase activity of GSK-3β." (PMID 36830642, 2023). "Therefore, we conclude that the role of METTL3/m6A in myocardial hypertrophy caused by different stimulating factors may depend on the function of the corresponding receptor with its downstream signaling." (PMID 35836108, 2022). "In contrast, METTL3 knockout accelerates pathological cardiac hypertrophy and heart failure by reducing m6A levels of poly (ADP-ribose) polymerase family member 10 (Parp10) mRNA and increasing PARP10 expression." (PMID 41446042, 2025). "Conversely, suppressing METTL3-mediated m6A modification inhibits cardiac hypertrophy to some extent, and this phenomenon is correlated with ALKBH5." (PMID 40290189, 2025). "Further, it is also shown that METTL3 is indespensible for cardiac homeostasis and cardiac hypertrophy, indicating the importance of both m6A methylase (e.g. METTL3) and demethylase (FTO) in cardiac function." (PMID 41327199, 2025). "METTL3-mediated m6A modification of OTU Deubiquitinase 1 (OTUD1) exacerbates pressure overload-induced cardiac hypertrophy by deubiquitinating PGAM5." (PMID 41194259, 2025). "A recent study demonstrated that cardiac-hypertrophy-associated piRNA (CHAPIR), a PIWI-interacting noncoding RNA (piRNA), directly interacts with Mettl3 to inhibit the m6A RNA methylation of Parp10 mRNA." (PMID 38706718, 2024). "USP12 deubiquitinated p300 to activate the transcription of methyltransferase-like 3 (METTL3), which resulted in the abnormal m6A RNA methylation in cardiomyocyte and exacerbated cardiac hypertrophy (Ref." (PMID 38525836, 2024). "Our research advances the understanding of OTUD1's role in cardiac hypertrophy and remodeling by elucidating the specific molecular mechanism involving the METTL3-mediated m6A modification of OTUD1 mRNA." (PMID 39309432, 2024). "To further validate role of METTL3 mediated OTUD1 RNA modification in cardiac hypertrophy in vivo, we used METTL3 inhibitor (STM2457) to treat AAV9-Otud1 mice." (PMID 39309432, 2024). "METTL3, as a “writer” protein, yields an opposite effect compared with “erasers” on cardiac hypertrophy in an m6A-dependent manner." (PMID 37273867, 2023). "Enhanced m6A leads to compensatory myocardial hypertrophy, while inhibition of m6A leads to muscle cell remodeling and dysfunction, highlighting the importance of METTL3-mediated methylation of m6A mRNA for maintaining normal cardiac function." (PMID 37063953, 2023). "In an in vivo model,cardiac-specific METTL3 knockout mice exhibited cardiac remodeling and HF,followed by dysregulation of cardiac homeostasis, while elevated levels of them6A RNA methyltransferase METTL3 led to cardiac hypertrophy." (PMID 39077559, 2023).
cardiac hypertrophy (continued). "It has been reported METTL3 directly regulate miR-221/222 by promoting miR-221/222 maturation in Ang-II-induced cardiac hypertrophy, subsequently activating the Wnt/β-catenin pathway." (PMID 37273867, 2023). "Upregulation of METTL3 reversed the decrease in myocardial hypertrophy induced by AngII in USP12-silenced NRCMs." (PMID 37273867, 2023). "In vitro analysis of METTL3 inhibition attenuates cardiomyocyte hypertrophy, indicating a role in the development of cardiac hypertrophy." (PMID 37034355, 2023). "Altogether, METTL3-induced miR-221/222 expression mainly promoted pathological cardiac hypertrophy in Ang-II via activating Wnt/β-catenin signaling." (PMID 35836108, 2022). "Taken together, these results demonstrate a protective role of MA against pressure-overload-induced cardiac hypertrophy by blocking METTL3-mediated m6A methylation." (PMID 35347085, 2022). "It is necessary to further clarify how METTL3 participates in the regulation of myocardial hypertrophy response to Ang-II stimulation." (PMID 35836108, 2022). "As activation of the Wnt/β-catenin pathway is vital in cardiac hypertrophy, it was selected as a potential mediator of METTL3–miR-221/222 to convey the hypertrophic effect." (PMID 35836108, 2022). "Since METTL3 knockout in the heart alone has been found to reduce cardiomyocyte cross-sectional area under aging without Ang-II stimulation, we evaluated only the effect of METTL3 knockdown on Ang-II-induced myocardial hypertrophy." (PMID 35836108, 2022). "Rescue experiments under adenovirus-mediated myocardial METTL3 overexpression confirmed that METTL3-mediated m6A methylation is essential in M-driven inhibition of myocardial hypertrophy." (PMID 35347085, 2022). "Overall, METTL3 inhibition treatment carried out by AAV9-delivery system had excellent performance in alleviating cardiac hypertrophy." (PMID 35836108, 2022). "Recently, several studies indicated a double-edged sword function of METTL3-m6A in regulating cardiac hypertrophy induced by different stimulating factors." (PMID 35836108, 2022). "The current study demonstrates a vital regulatory role of METTL3 in Ang-II-induced cardiac hypertrophy." (PMID 35836108, 2022). "The depletion of METTL3 abrogated the hypertrophy of cardiomyocytes, while increasing METTL3 level led to compensated cardiac hypertrophy." (PMID 36178367, 2022). "We further found that METTL3 knockdown significantly alleviated Ang-II stimulated cardiomyocyte remodeling, suggesting that METTL3 is involved in the formation of Ang-II-induced myocardial hypertrophy." (PMID 35836108, 2022). "Overexpression of METTL3 induces remodeling in compensatory cardiac hypertrophy via mitogen-activated protein (MAP)3K6, MAP4K5, and MAPK14, without causing cardiovascular function defects in basal or stressed state." (PMID 35406663, 2022). "Knockout of METTL3 inhibits the progress of cardiac hypertrophy, while overexpression of METTL3 promotes the cardiac hypertrophy." (PMID 34489709, 2021). "CHAPIR regulates the cardiac hypertrophy by controlling the METTL3 dependent m6A methylation of PARP10 mRNA." (PMID 34489709, 2021). "METTL3 mediated m6A modification is enhanced by hypertrophic stimulation, which is necessary for cardiac hypertrophy." (PMID 34489709, 2021). "Aging can induce heart hypertrophy as a modest and long-term chronic stressor, and different regulators that address cardiac aging pressure demonstrate differential responsiveness 47; the same is likely true for METTL3 and Nsun2." (PMID 39990213, 2025). "The piRNA CHAPIR is identified as the upstream of METTL3.331CHAPIR regulates cardiac hypertrophy by interacting with METTL3 and inhibiting its methylase activity, leading to the hypomethylation of the ADP-ribosyltransferase Parp10 mRNA and the inhibition of YTHDF2-mediated degradation." (PMID 37884527, 2023).
cardiac hypertrophy (continued). "USP12 inhibits the degradation of p300 by deubiquitinating its K48-linked polyubiquitination chains and stabilizes p300 protein, which in turn promotes METTL3 transcription via enhancing METTL3 promoter activity and eventually exacerbates Ang II-induced cardiac hypertrophy." (PMID 37752518, 2023). "For example, USP12 overexpression could exacerbate Ang II-induced cardiac hypertrophy by raising the METTL3 level." (PMID 37752518, 2023). "However, METTL3 knockdown also accelerates heart failure progression by promoting pathological cardiac hypertrophy through upregulating the expression of PARP10." (PMID 35836571, 2022). "AAV9-mediated cardiac METTL3 knockdown could be a therapeutic for pathological myocardial hypertrophy." (PMID 35836108, 2022). "Finally, AAV9-mediated cardiac METTL3 knockdown was able to attenuate Ang-II-induced cardiac hypertrophy in mouse model." (PMID 35836108, 2022). "PiRNA CHAPIR promotes cardiac hypertrophy through METTL3-mediated m6A modification of Parp10 mRNA." (PMID 35191812, 2022). "To clarify whether miR-221/222 was directly regulated by METTL3 in Ang-II-induced cardiac hypertrophy, we evaluated the expression of these two miRNAs and confirmed that miR-221/222 was upregulated in Ang-II-stimulated cardiomyocytes." (PMID 35836108, 2022). "We further evaluated the action of METTL3 knockdown on the cardiac hypertrophy in vivo." (PMID 35836108, 2022). "Recently, METTL3 was reported to be upregulated in Ang-II-induced myocardial hypertrophy." (PMID 35836108, 2022). "However, the specific mechanism of METTL3 function in Ang-II-induced cardiac hypertrophy is still unclear." (PMID 35836108, 2022). "METTL3 overexpression was sufficient to promote cardiac hypertrophy." (PMID 35461308, 2022). "Moreover, through adenovirus-mediated myocardial METTL3 overexpression, the present study demonstrated that METTL3-mediated m6A contributes to MA-driven inhibition of myocardial hypertrophy." (PMID 35347085, 2022). "METTL3 therefore appears to be a detrimental agent in murine hypoxic cardiomyocytes in vitro and in infarcted myocardium, akin to the earlier discussion for cardiac hypertrophy." (PMID 35991314, 2022). "In addition to its role in cardiac hypertrophy, METTL3 has also been shown to play a critical role in myocardial infarction." (PMID 34221238, 2021). "METTL3 may be a deleterious factor in the development of cardiac hypertrophy." (PMID 41194259, 2025). "However, the key methyltransferase METTL3 may play an important role in cardiac hypertrophy, and studies have found that METTL3 may be a key regulatory factor in increasing m6A methylation levels after hypertrophy." (PMID 35953789, 2022). "However, whether and how METTL3 plays a role during angiotensin II (Ang-II)-induced myocardial hypertrophy is still unknown." (PMID 35836108, 2022). "METTL3 positively regulates PRI-MIR221/222 maturation in an M6A-dependent manner and subsequently promotes Ang-II-induced cardiac hypertrophy by inhibiting DKK2 activation of Wnt/β-catenin signaling." (PMID 36959563, 2023). "Thus, METTL3 could mediate the Ang-II-induced myocardial hypertrophy by upregulating miR-221/222." (PMID 35836108, 2022). "Overexpression of METTL3 promotes compensatory cardiac hypertrophy without impacting cardiac function." (PMID 41446042, 2025). "Our findings suggest that METTL3 positively modulates the pri-miR221/222 maturation process in an m6A-dependent manner and subsequently activates Wnt/β-catenin signaling by inhibiting DKK2, thus promoting Ang-II-induced cardiac hypertrophy." (PMID 35836108, 2022). "Increased expression of METTL3 promoted spontaneous, compensated cardiac hypertrophy in mice without affecting cardiac function when exposed to stress; whereas cardiac-specific METTL3 knockout induced structural and functional changes similar to HF in mice hearts exposed to stress." (PMID 35571209, 2022).
hepatoblastoma (33 papers, 2019 to 2025). Hepatoblastoma (HB) is a malignant hepatic tumor and is the most common pediatric liver cancer. "In hepatoblastoma, METTL3 is associated with cancer development through Wnt/β-catenin signalling pathway and considered as a prognosis predictor." (PMID 34011074, 2021). "Our group has previously reported that many genetic variants of genes encoding RNA m6A and m7G methyltransferase, demethylase, and m6A-reading proteins confer hepatoblastoma susceptibility, including METTL3, METTL4, AlkB homolog 5 (ALKBH5), FTO, YTHDC1, YTHDF1, WTAP, WDR4, and METTL1." (PMID 37531210, 2023). "High METTL3 levels are associated with continual recurrence and poor prognosis of hepatoblastoma patients, suggesting that METTL3 could be used as a potential diagnostic and prognostic biomarker for hepatoblastoma patients." (PMID 34616742, 2021). "In hepatoblastoma (HB), METTL3/m6A methylation significantly affects the Wnt/β-catenin pathway by decreasing the expression and stability of CTNNB1, the coding gene of β-catenin." (PMID 40136363, 2025). "Emerging evidence suggested that METTL3 made a partially important contribution to ferroptosis in LC and hepatoblastoma." (PMID 38221933, 2024). "Recent research has revealed an increase in m6A modifications in hepatoblastoma, with METTL3 being the primary factor responsible for these abnormal m6A modifications." (PMID 38390281, 2024). "In hepatoblastoma, a rare liver cancer usually diagnosed during the first 3 years of life, the upregulation of METTL3, YTHDF2, and FTO has been correlated with poor clinical outcomes." (PMID 37369946, 2023). "METTL3-mediated m6A modification of SLC7A11 promotes ferroptosis resistance in hepatoblastoma cells." (PMID 38072908, 2023). "miR‐186 and METTL3 jointly contributed to cell proliferation as well as distant migration in hepatoblastoma." (PMID 36162823, 2023). "We have previously shown that several RNA m6A-mediated genes (i.e., METTL3, METTL14, WTAP, YTHD1, YTHDC1, and ALKBH5) are associated with hepatoblastoma susceptibility." (PMID 35986847, 2022). "In another study, METTL3 was identified as a direct target of microRNA-186, which is weakly expressed in hepatoblastoma tissue." (PMID 36008936, 2022). "In hepatoblastoma (HB), METTL3-mediated m6A was reported to directly target β-catenin mRNA, leading to tumor growth in vitro and in vivo." (PMID 34315512, 2021). "For example, in hepatoblastoma, upregulation of METTL3 promotes the proliferation, migration, and invasion of hepatoblastoma cells by activating the Wnt/β-catenin signaling pathway." (PMID 34616742, 2021). "In hepatoblastoma, METTL3 is identified as a direct target of hsa-miR-186, and the hsa-miR-186/METTL3 axis participates in the progress of hepatoblastoma through the Wnt/β-catenin signaling pathway." (PMID 33708621, 2021). "In hepatoblastoma (HB) cells, knockout of METTL3 notably inhibited the proliferation, migration, and invasion of cells." (PMID 34108450, 2021). "It has been reported that the RNA METTL3 and miR-186 regulate hepatoblastoma progression through the Wnt/β-catenin signaling pathway." (PMID 33519919, 2020). "METTL3 is significantly upregulated in hepatoblastoma, and it regulates β-catenin to promote tumor proliferation." (PMID 32974164, 2020). "In hepatoblastoma, METTL3 promotes development of hepatoblastoma development through increasing the expression of CTNNB1 via regulation of the Wnt/β-catenin pathway." (PMID 32513173, 2020). "In this research, we discovered that m6A modifications are increased in hepatoblastoma, and METTL3 is the main factor involved with aberrant m6A modification." (PMID 31870368, 2019). "Overall our findings suggest enhanced m6A mRNA methylation as an oncogenic mechanism in hepatoblastoma, METTL3 is significantly up-regulated in HB and promotes HB development." (PMID 31870368, 2019).
hepatoblastoma (continued). "Similarly, in hepatoblastoma, METTL3-mediated m6A modification increases the stability and expression of SLC7A11 mRNA, conferring resistance to ferroptosis and accelerating tumor growth." (PMID 40271153, 2025). "As an independent prognostic factor in hepatoblastoma patients, METTL3 was identified as a direct target of miR-186, of which low level led to high expression of METTL3, thus significantly inhibiting the proliferation, migration and invasion of hepatoblastoma cells." (PMID 36614216, 2023). "In hepatoblastoma, bioinformatic software discovered miR‐186 as a regulatory molecule of METTL3." (PMID 36162823, 2023). "The miR-186/METTL3 axis promoted the proliferation and migration of Hepatoblastoma cells through the Wnt/β-catenin signaling pathway, which might be a target for the treatment of Hepatoblastoma." (PMID 36531231, 2022). "Interestingly, upregulated METTL3 was reported to promote β-catenin and c‐Myc expression, and mainly affect the biological progression of hepatoblastoma through the Wnt/β‐catenin pathway." (PMID 35836108, 2022). "Mechanistically, methylation of CTNNB1 transcripts by METTL3 increases the expression of β-catenin, which is involved in the regulation of tumor immunity, thereby increasing the proliferation and tumorigenicity of hepatoblastoma cells." (PMID 35254013, 2022). "While high level of METTL3 or YTHDF2 can be used as the poor prognostic factor for hepatoblastoma." (PMID 33708621, 2021). "However, research on the role of METTL3 and the m6A machinery in cancers including hepatoblastoma still in its early stage, indicating an urgent need to head light on future clinical cancer therapy and drug developments." (PMID 31870368, 2019). "METTL3 knockdown in hepatoblastoma cells could suppress proliferation, invasion, and migration." (PMID 37369946, 2023). "In-depth studies have revealed that METTL3 strengthened the expression of SLC7A11, which is a crucial negative regulator of ferroptosis, by means of its N6-methyladenosine (m6A) activity in hepatoblastoma and LC." (PMID 38221933, 2024). "METTL3/IGF2BP1-mediated m6A modification stabilizes SLC7A11 mRNA and upregulates SLC7A11 expression by inhibiting the deadenylation process in hepatoblastoma cells." (PMID 38072908, 2023). "For example, METTL3-mediated m6A mRNA methylation promoted the proliferation of hepatoblastoma through the regulation of CTNNB1, while METTL3 promoted temozolomide resistance by increasing the expression of MGMT and ANPG." (PMID 35571106, 2022). "The m6A regulators METTL3, WTAP, FTO and YTHDF2 are elevated in tumor vs control tissues from hepatoblastoma patients and all four regulators contributed to the proliferation and colony formation of HepG2 cells." (PMID 36008936, 2022). "In hepatoblastoma cells, increased METTL3 activity resulted in increased m6A deposition on Ctnnb1, leading to aberrant activation of the WNT/CTNNB1 pathway, which promoted hepatoblastoma cell growth." (PMID 35350378, 2022). "For instance, compared with adjacent non-tumor tissues, METTL3 expression is upregulated in hepatoblastomas." (PMID 34616742, 2021).